CD24 (CD24 molecule)
Diseases named in the same sentence as CD24 in open-access papers (continued):
Sharing a sentence is not in itself a finding about the gene and the disease.
tumor (continued). "There are limited studies on improving the tumor‐phagocytosis capability of macrophages by blocking PD‐L1‐PD‐1, MHC‐I‐LILRB1, and CD24‐Siglec‐10 phagocytic immune checkpoint." (PMID 37323705, 2022). "In tumor cells isolated from primary HCC tissues, pearson correlation analysis revealed that MUC15 levels were negatively correlated with the expression of CD24 and EpCAM." (PMID 35236826, 2022). "In contrast, some inhibitory ICR/ICL pairs such as CD24-SIGLEC10 and LGALS9-HAVCR2 were frequently observed between myeloid cells, master cells, B cells and tumor cells." (PMID 36172359, 2022). "Markers CD24, CD44, PDX1, synaptophysin, CD49, CDX2, CD45, DAXX, PCAD and CK7 had lower expression in the tumour relative to that in the non-tumour with the exception of one patient." (PMID 36362433, 2022). "Coincident upregulation of both epithelial and mesenchymal genes was observed in the majority of blood-derived CTC samples compared to primary tumour, while a few epithelial genes such as CLDN7, CD24 and CDH1 were downregulated in the CTC samples." (PMID 34206049, 2021). "We then revealed that CSC score (based on CD44, CD24, and ALDH1A1) was correlated with tumor progression and TB." (PMID 35083162, 2021). "mRNA levels of Ki-67, CD24, CD44, CD31, MENA, CD49, ECAD, PCAD, EpCAM, CDX2, CK6, CK7, CK13, were significantly decreased in tumour tissue relative to non-tumour tissue." (PMID 33906633, 2021). "Other markers including Ki67, PCNA, DAXX, CD24, CD44, CD31, MENA, Laminin, ECAD, PCAD and CDX2 and CK14 showed different trends in expression between tumour and non-tumour with qRT-PCR compared to IHC." (PMID 33906633, 2021). "Tumor cells isolated from HTM (black histogram) showed similar expression profiles of cMET and CD24 and slightly different HER2 and CD47 patterns compared to cell culture cells (grey histogram)." (PMID 34070094, 2021). "Pancreatic cancer stem cells (PCSCs) promote tumor growth and progression through several mechanisms, including tumor-initiation by inducing stem cell markers CD44, CD24, and CD133, and evasion of conventional therapies." (PMID 34820419, 2021). "Compared to MDA-MB-231 and RT-R-MDA-MB-231 cells, CD24−/low/CD44+ cells isolated from RT-R-MDA-MB-231 cells showed increased proliferation, migration and invasion abilities, and induced expression of tumor progression-related molecules." (PMID 34502547, 2021). "mRNA levels of Ki67, CD24, CD44, CD31, MENA and ECAD were reduced in tumour tissue relative to normal tissue, whereas the protein expression was increased in the tumour compared to normal tissue." (PMID 33906633, 2021). "Finally, HPGD which encodes the PGE2 signal terminator 15-PGDH is significantly upregulated in the CD44+/CD24- tumor cells; this could negate any increased production of PGE2 cells due to increased PLA2/COX-2, since increased 15-PGDH would degrade produced PGE2." (PMID 35127497, 2021). "Combined treatment of AA-TNBC-derived tumors with GANT61, DAPT, and doxorubicin/carboplatin results in significant tumor regression, and tumor-dissociated cells show mitigated migration, invasion, mammosphere formation, and CD44+/CD24- population." (PMID 34889737, 2021). "This cell phenotype has been further refined whereby CD44+CD24-/low cells expressing active ALDH1, enriched following doxorubicin treatment, were able to reproduce the bulk tumour in a mouse xenograft model." (PMID 33799834, 2021). "On the other hand, OvCA malignant ascites-derived exosomes display a cargo of tumor progression related proteins, such as L1CAM, CD24, ADAM10, and EMMPRIN, which have been found to correlate with worse prognosis." (PMID 34768926, 2021). "While tumor cells undergo EMT, some studies have determined downregulation (as seen during TGF-β-dependent EMT), while others have observed upregulation of CD24 expression." (PMID 34453639, 2021).
tumor (continued). "In an in vivo model, CD24−/low/CD44+ cell-injected mice showed enhanced tumor progression and lung metastasis via upregulation of tumor progression-related molecules and altered host immune responses." (PMID 34502547, 2021). "In the ectopic tumour model receiving castration and bicalutamide therapy, massive solid tumours were observed in ALDH+CD44+CXCR4+CD24+-cell-injected mice, whereas the ALDH−CD44−CXCR4−CD24− cells yielded smaller tumours." (PMID 34247196, 2021). "It is recently discovered that the tumor conveys the "don't eat me" signal of innate immune surveillance through CD47‐SIRPα5 and CD24‐Siglec‐106 action." (PMID 34363319, 2021). "Tumor-dissociated cells, examined for the presence of stemness marker CD44+/CD24-, showed higher stemness in vehicle-treated group (87.6%) compared to triple-therapy-treated tumors (48.6% for DGD and 65.2% in CGD)." (PMID 34889737, 2021). "It was correlated with high-grade tumours and poor overall survival and involved in ALDH+CD44+CXCR4+CD24+-cell-rendered castration resistance." (PMID 34247196, 2021). "Effective inhibition of tumor growth was achieved using the INS peptide (1.25 mg/kg) that was injected, along with the CD24-targeted lentiviral particles, twice weekly for two weeks." (PMID 33958722, 2021). "Thus, binding of cancer cells to P-selectin via CD24 may be crucial for inducing tumor metastasis." (PMID 33889547, 2021). "By comparing the gene expression profiles of orthotopic and subcutaneous PCa tumours, we selected five widely used CSC markers (ALDH, CD44, CXCR4, α2β1 and CD24) to sort candidate PCSCs from orthotopic PCa tumours." (PMID 34247196, 2021). "CD24, CD74, PGK1 showed significantly higher expression in tumour tissue compared with tumour adjacent normal tissue, while STX11 and NFKBIA showed the opposite trend (p < .001 for all)." (PMID 34187256, 2021). "“Don’t eat me” signaling pathways, such as CD47-SIRPα, the MHC-I-LILRB1 axis, and the CD24-SIGLEC-10 axis can be expressed by all types of macrophages and play crucial roles in inhibiting macrophage phagocytosis of tumor cells in numerous cancer types." (PMID 34778091, 2021). "The mRNA levels of CSCs markers (CD44 and CD24) and EMT markers (E-cadherin, β-catenin, vimentin, and N-cadherin) in tumor tissues were analyzed with qRT-PCR." (PMID 33282946, 2020). "CD24 is internalized in cells after the binding of SWA11mAb, and the role of the SWA11 monoclonal antibody is mainly to reduce the proliferation of tumor cells." (PMID 32765491, 2020). "CD24 overexpression was observed in the WERI‐Rb‐1 and Y79 cell lines with in vivo tumor‐forming ability." (PMID 32394616, 2020). "CD24/Siglec-10 can inhibit the activation of T cells mediated by TCR and promote tumor immune escape." (PMID 32765491, 2020). "In same tumor model, lnc-DILC expression in CD24+/EpCAM+ hepatic CSCs connects hepatic inflammation with liver CSC expansion, with low lnc-DILC levels to be predictive of early tumor recurrence and poor patient survival rates." (PMID 32932969, 2020). "CD24 positive tumors are reported to have a poor prognosis, and CD44 depletion has been shown to inhibit tumor proliferation and augment the effect of cytotoxic drugs." (PMID 33322363, 2020). "Expressions of CD90, EpCAM, CD133, CD24, SOX9, CD44, CK19, and CD47 were positively related to immune infiltration level in HCC, negatively related to tumor purity." (PMID 32184801, 2020). "CD44, CD133, CD24, and ALDH activity are frequently used for the detection and isolation of CSCs from tumor tissues and many cancer cell lines." (PMID 32814771, 2020). "All SCLC CTCs are CD24-positive but lack expression of CD44 and ABCG2 in contrast to the SCLC tumor lines which show a phenotype more similar to that of CSCs." (PMID 31446534, 2020). "BCSCs have been isolated from tumor samples and breast cancer cell lines using a combination of surface markers such as CD44, CD24, EpCAM, CD133 and ALDH, among others." (PMID 32183150, 2020).
tumor (continued). "The PCSCs isolated from AR-negative DU145 cells show higher expression of CD44, CD24, integrin α2β1, cellular reprogramming factor SOX2, and exhibit tumor-initiating potential and self-renewal ability." (PMID 32754615, 2020). "In recent years, CD24 has evolved as an encouraging molecular biomarker for EOC in the field of immunotherapy, and as a tumor-specific biomarker for targeted drug delivery and imaging." (PMID 33260974, 2020). "Al-Hajj and colleagues were the first to identify tumor-initiating CSCs in BC by using cell surface markers CD44 and CD24." (PMID 33327542, 2020). "The counts of CD44+CD24− BCSCs and CD44+CD24−CD44+ BCSCs were also significantly decreased in the tumor tissues of mice treated with the miR-7 agomir and in the Ad plus Cy group." (PMID 32143670, 2020). "CD24 was co-expressed with CD133 in NCI-H69, DMS53, and GLC14 tumor cells and detectable in all CTC SCLC cell lines." (PMID 31446534, 2020). "Compared with the traditional 2D cultured tumor cells (2D-HepG2), 3DP-HepG2 showed significantly improved expression of tumor-related genes, including ALB, AFP, CD133, IL-8, EpCAM, CD24, and β-TGF genes." (PMID 32582546, 2020). "Via phosphorylation of STAT3, CD24 induces NANOG, a key factor for self-renewal in embryonic stem cells and during tumor development, thus enabling HCC cell self-renewal." (PMID 32183251, 2020). "Tumors were dissociated into single-cell suspensions before sorting for epithelial CD24+ Lin- (CD31- CD45- Ter119-) cells, to enrich for tumor cells and reduce stromal cell contamination." (PMID 32840210, 2020). "During the study of stem characteristics in tumor cells, it is necessary to use at least these three markers (CD44/CD24, CD133, and ALDH1)." (PMID 32316333, 2020). "Here, we review the emerging tumor-specific biomarker CD24 as a target for FIGS, and focus specifically on EOC and the use of CD24 as a bimodal biomarker for both imaging and theranostics." (PMID 33260974, 2020). "Expression of different modulators of immune responses such as CD73, CD38, CD24, CD47 and many more can be evaluated on tumor cells, immune cells, or as soluble markers in BAL." (PMID 35582213, 2020). "CD24 was significantly expressed in the CTC SCLC cell lines, as well in NCI-H69, DMS53, DMS273, GLC14 tumor cells with exception of DMS114." (PMID 31446534, 2020). "We further detected the protein expression of CD24, PTEN, and cleaved LC3 in the tumor tissues by IHC." (PMID 32394616, 2020). "The ability of α‐Mangostin to inhibit pancreatic CSC markers CD24, CD44 and CD133 demonstrate that it can modulate the tumour growth by the suppression of the CSC population." (PMID 30712329, 2019). "To assess the tumor-initiating cells/cancer stem cell (TIC/CSC) population, we undertook a flow cytometric analysis using standard CSC markers such as CD24 and CD4411, 12 and CD90." (PMID 30442981, 2019). "CD24 is an extracellular glycoprotein and cell membrane marker in CSC, and is known to increase tumor growth and promote metastasis." (PMID 30813586, 2019). "It has been reported that CD24 regulates NANOG expression through STAT3 phosphorylation and that pSTAT3 (Y705) bound to the NANOG promoter drives tumor onset and self-renewal in the liver." (PMID 30804456, 2019). "The results showed that the number and diameter of tumour spheres formed and the proportion of CD44+CD24− phenotype cells from SKBR3‐S were noticeably decreased." (PMID 31599500, 2019). "In anchorage independent growth assays, overexpression of CD24 and CD133 produced larger tumor spheres than puro controls at 2 weeks." (PMID 30467381, 2019). "Given its published identification as a putative marker of stem/progenitor cells, we investigated the tumour propagating potential of CD133 and its co-labelling potential with CD24." (PMID 30657775, 2019).
tumor (continued). "Other cell surface antigens expressed on tumor cells can serve as adhesive receptors for platelets, including podoplanin: CLEC2, the HMGB1: TLR4, and the CD24: P-selectin interactions." (PMID 31623163, 2019). "The tumor sphere cells isolated from 4 T1 parental cells were CD44 + CD24-, while parental cells were CD44 + CD24+." (PMID 31196164, 2019). "Most tumor sphere cells were CD44 + CD24-, while only 1.16 ± 0.95% parental cells were CD44 + CD24-." (PMID 31196164, 2019). "Administration of an LSD1 inhibitor hampered tumor growth, but the most significant finding was that it also led to a pronounced reduction of the stem-like CD44+CD24-/low subpopulation." (PMID 31627418, 2019). "CD133high or CD44+CD24- cells or CD133+CD44+ cells have been isolated from DU145 and PC3 cell lines and have been shown to be able of inducing colony tumor formation in vitro and tumor formation in vivo after subcutaneous injection in mice." (PMID 31366128, 2019). "Bulk tumor cells were defined by the Epi+ cells expressing epithelial lineage (Epi) markers EPCAM and CD24." (PMID 31115187, 2019). "CSC markers included CD24, CD44, and SNAIL; CSC properties included tumor sphere formation, migratory capacity, and tumor initiation." (PMID 31036052, 2019). "We found that the number and diameter of tumour spheres formed per 100 cells and the proportion of CD44+CD24− phenotype cells were significantly reduced in SKBR3‐S but not MCF‐7‐S cells after stable transfection of a lentiviral vector encoding miR‐200c." (PMID 31599500, 2019). "Jahchan and coworkers have isolated and characterized a population of long-term tumor-propagating cells in a mouse model of SCLC; this population is characterized by high levels of CD24 and EpCAM expression and was identified also in primary human SCLCs." (PMID 30060526, 2018). "The high-CD24-expressing cells, isolated from patient-derived UCB xenograft tumours, exhibited their enhanced stemness properties." (PMID 30327565, 2018). "While essentially all Cd24−/− mice had visible tumors at 7 months in this experiment, Cd24−/− livers had more tumors than WT livers, as measured either by the numbers of observable HCC lesions or by the total tumor volumes." (PMID 29423273, 2018). "It is well documented that cancer cells positive for the cell surface antigens CD24, and CD44 exhibit increased self‐renewal and tumor‐initiating potential." (PMID 30318866, 2018). "Using FACS-based single-cell analysis, we examined the stem cell fate of freshly isolated tumor cells using common cancer stem cell markers, including CD44, CD24, and CD49f for breast CSCs." (PMID 29510720, 2018). "Different subsets of circulating tumor cells were determined on the basis of the expression of EpCAM, CD45, CD44, CD24, and N-Cadherin using flow cytometry." (PMID 29565320, 2018). "Therefore, modulation of the radiosensitivity of these cells could be exclusively ascribed to genetic reprogramming/dedifferentiation due to production of CD24−/low/CD44+ stem-like cells in the tumor through epigenetic changes induced by epithelial mesenchymal plasticity." (PMID 29805752, 2018). "lnc-DILC, which is downregulated in EpCAM+, CD24+, or OV6+ liver CSCs, has a tumor suppressive function." (PMID 29888282, 2018). "In another study, tumors with stem cell markers, CD44+/CD24–/Lin– and ALDH1, grown as mammospheres showed an increased capacity for tumor initiation in xenograft models." (PMID 30542507, 2018). "In breast cancers, tumor cells undergoing EMT gain CSC properties, including the ability to self-renew and tumorigenicity, and exhibit a CD24−/low/CD44+ phenotype." (PMID 29805752, 2018). "We next looked at the surface expression of CD24 and CD44 by flow cytometry, in which the CD24-/CD44+ population is indicative of potential tumor initiating cells (TIC) with invasive and drug resistance capabilities." (PMID 29879129, 2018). "In contrast, only three luminal markers showed immuno-staining in the tumor transplants (KRT7, KRT19, and CD24)." (PMID 30550540, 2018).
tumor (continued). "The expression levels of these three molecules (CD24, CD49f, and NANOG) in primary tumour tissues were significantly higher in subjects with positive expression in urine samples than in those with negative urine expression." (PMID 30327565, 2018). "They found that a small fraction of cells exhibiting CD44+/CD24−/Lineage (Lin)− phenotype on surface had higher tumor-forming ability in immunocompromised mice and self-renewal property in reiterated passage than CD44+/CD24+/Lin− cells." (PMID 28445439, 2017). "PL21 showed a focal amplification in chromosome 6 and 17 of the primary tumor, which was also seen in unsorted cells and in the CD44+/CD24-/low subpopulation." (PMID 28423035, 2017). "Half of the mice injected with 100 CD44+CD24+ESA+ cells formed tumors, compared with 10000 triple-negative cells, which only 1 in 12 mice developed a tumor." (PMID 28245823, 2017). "The tumor size and weight from the CD47-CAR-T cell-treated group were significantly less (p < 0.05) than from the control 1× PBS and CD24-CAR-T cell groups." (PMID 29065481, 2017). "Recent reports demonstrated that a hybrid epithelial/mesenchymal CD44+/CD24-/ALDH+ CSC subpopulation is more tumorigenic then its pure counterpart, although its role in metastasis and secondary tumor formation remains to be elaborated." (PMID 29348905, 2017). "Whole-genome CNA analysis in FACS-sorted CD44+/CD24− and CD44−/CD24+ cells from three human NSCLC tumors and a tumor-derived cell line showed that the CD44+/CD24− cells possessed a higher content of DNA joint points and the distinctive saw-tooth profile." (PMID 28092266, 2017). "In PC, CSCs have initially been identified by being characterized as CD44+CD24+ESA+cells and having the ability to form tumors at a much higher frequency than the bulk tumor." (PMID 28245823, 2017). "An in vivo serial transplantation assay was performed using CD24, CD44 and EpCAM-selected cells from xeno-B110 to determine if they were able to self-renew by initiating new tumours up to the fourth generation." (PMID 28959019, 2017). "The CD44, CD24, HER2, and epithelial cell adhesion molecule (EpCAM) expression on BT474 and SK-BR-3 tumor cells was assessed by flow cytometry as a function of tumor treatment." (PMID 27835865, 2017). "AZD4547 also depleted CD24/CD49f-sorted MEC populations, as well as the CD61highCD49fhigh tumor-initiating cell-enriched population." (PMID 28900173, 2017). "The statistical analysis showed that coexpression of ANXA10 and CD24 was highly correlated with PDAC and high-grade neoplasia lesions." (PMID 28369074, 2017). "Stemness was determined by tumour sphere formation in both soft agar and liquid cultures as well as by the expression of CD44/CD24/ALDH markers." (PMID 28341962, 2017). "Double immunostaining of ANXA10 and CD24 showed that there was a large overlap between these two markers in PDAC and high-grade neoplasia lesions." (PMID 28369074, 2017). "We defined a parameter CD44/CD24 ratio to present the expression level of CD44 and CD24 and found that high CD44/CD24 ratio and ALDH1+ are both indicators for cancer malignancy, but play different functions during tumor progression." (PMID 29062075, 2017). "In particular, CD24 has been shown to enhance the activation of signal transducer and activator of transcription 3 (STAT3) in different tumor types." (PMID 28320418, 2017). "Using flow cytometry, CSCs can be distinguished from the bulk of the tumor by their expression of cell surface makers CD44 and CD24 (as a CD44(+)CD24(-/low) subpopulation) and based on the activity of ALDH1." (PMID 28270211, 2017). "Owing to an extremely low level of CD24 positive cells in C666-1, only CD44, EpCAM and EpCAM/CD44-selected cells from C666-1 were evaluated for their tumour-initiating ability in NSG mice." (PMID 28959019, 2017).